CDK8 (cyclin dependent kinase 8)
Diseases named in the same sentence as CDK8 in open-access papers (continued):
Sharing a sentence is not in itself a finding about the gene and the disease.
prostate carcinoma (25 papers, 2015 to 2026). A carcinoma that arises from epithelial cells of the prostate gland. "Cancer cells are prevented from proliferating when T-474 or T-418 (two structurally differentiated CDK8/19 enzyme inhibitors) are used to treat prostate cancer that is susceptible to these drugs." (PMID 38606172, 2024). "An analysis of data in The Cancer Genome Atlas (TCGA) shows that high CDK19 and CDK8 levels in prostate cancer are also associated with a high migratory potential." (PMID 31248103, 2019). "In particular, amplification and overexpression of CDK8 have been found in colon, breast, and prostate cancers, which underlies the marked attention that CDK8 has attracted as a potential target for cancer therapy by small molecule inhibitors." (PMID 29568371, 2018). "This suggests that the direct inhibition of CDK8/19 may affect prostate cancer cells similarly to what was observed with MED12 loss." (PMID 39253786, 2024). "Given that leukemic cells are sensitive to the dosage of super-enhancer-associated genes affected by CDK8/19 inhibition, the possibility exists that certain prostate cancer cells such as VCaP cells may also show vulnerability to the activation of super-enhancer-associated genes." (PMID 29568371, 2018). "CDK8 is an androgen-repressed factor that remains unchanged in benign prostate tissue and primary prostate cancer." (PMID 40163908, 2025). "Recently, a study reported reduced migration and invasion of different prostate cancer cell lines in response to two other CDK8/CDK9 inhibitors, CCT251545 and G02788177.93–1 [,196]." (PMID 40163908, 2025). "Increased levels of CDK8 and CDK19 are associated with a higher migratory potential in prostate cancer cell lines." (PMID 40163908, 2025). "Subsequently, another study revealed a novel CDK8 inhibitor, E966–0530–45,418, that potently inhibited migration of prostate cancer cells and demonstrated anti-metastatic properties in CRPC xenografts." (PMID 40163908, 2025). "Despite providing novel insights into the role MED12 and CDK8/19 in prostate cancer, our study has several limitations." (PMID 39253786, 2024). "Taken together, these results suggest that MED12 and CDK8/19 play important roles in promoting tumorigenesis and resistance to therapy in prostate cancer cells." (PMID 39253786, 2024). "In prostate cancer cell lines, CDK8 protein expression was higher in PC3 cells than in LNCaP and 22Rv1 cells." (PMID 39253786, 2024). "Our study investigated how the inhibition of MED12 and CDK8/19 subunits affects cancer signaling pathways and cell processes in prostate cancer, focusing on AR activity and cell responsiveness to enzalutamide." (PMID 39253786, 2024). "We showed that MED12 and CDK8/19 inhibition downregulate the AR response and that they both affect prostate cancer cell response to enzalutamide." (PMID 39253786, 2024). "In this study, we investigated how MED12 and CDK8/19 influence cancer-driven processes in prostate cancer cell lines, focusing on AR activity and the enzalutamide response." (PMID 39253786, 2024). "In conclusion, our study highlights the involvement of MED12 and CDK8/19 in c-Myc, AR activity, and cell response to enzalutamide in prostate cancer." (PMID 39253786, 2024). "Increased cyclin‐dependent kinase 8 (CDK8) expression has been found in several cancers, such as colorectal, hematological, breast, and prostate cancer." (PMID 38723187, 2024). "Inhibition of Mediator kinases CDK19 and CDK8 suppresses androgen-independent in vivo growth of castration-resistant prostate cancers via castration-induced transcriptional reprogramming in tumor and stromal cells." (PMID 38546787, 2024). "Our findings regarding the impact of CDK8/19 on prostate cancer suggest promising avenues for therapeutic interventions." (PMID 39253786, 2024). "Clarifying the roles of MED12 and CDK8/19 in modulating AR and AR-Vs is crucial for understanding their impact on prostate cancer." (PMID 39253786, 2024).
prostate carcinoma (continued). "In prostate cancer cells, CDK8/19 inhibition downregulates cell proliferation and in vivo metastasis formation." (PMID 39253786, 2024). "In prostate cancer, miR-372 negatively regulates CDK8 and induces G0/G1 blockade, impeding the proliferation of cancer cells." (PMID 38606172, 2024). "Several CDK8/19 inhibitors were recently tested as potential anticancer drugs in acute myeloid leukemia, prostate cancer, and other diseases." (PMID 37298278, 2023). "We also generated derivatives of 22Rv1 prostate cancer cells (which overexpress CDK19 relative to CDK8) with the knockout of CDK8 and CDK19, individually and in combination (dKO), and analyzed STAT1 S727 phosphorylation with and without IFNγ treatment." (PMID 37378433, 2023). "Elevated mediator complex sub-type CDK19 expression associated with aggressiveness of prostate cancer; Pan-Cancer Analysis of the Mediator Complex Transcriptome determined CDK19 and CDK8 as treatment targets in late-period prostate carcinoma." (PMID 35627232, 2022). "CDK19 is a paralog of CDK8 and was identified as a therapeutic target in prostate cancer and leukemia." (PMID 33686962, 2021). "Knockdown or inhibition of CDK8/CDK19 kinase in prostate cancer cell lines has a relatively minor impact on cell viability, but significantly reduces migration and invasiveness." (PMID 31248103, 2019). "In contrast, at the protein level, CDK19 expression in tumor cell lines (other than prostate cancer) is generally much lower than the expression of CDK8 (our unpublished data), suggesting post-transcriptional regulation of CDK19." (PMID 31382571, 2019). "Both deletions and amplifications were especially notable among prostate cancers, where increasing expression of CDK19 and CDK8 has been shown to be associated with carcinogenesis and acquisition of the largely incurable CRPC phenotype." (PMID 31382571, 2019). "We show that highly selective CDK8/19 inhibitors exerted anti-proliferative activity in prostate cancer cells both in vitro and in vivo." (PMID 29568371, 2018). "To address this deficit, in this preclinical study, we used both small molecule inhibitors of CDK8/19 and genetic approaches to investigate the dependence of prostate cancer cells on CDK8/19 activity." (PMID 29568371, 2018). "Our data provide a rationale for further investigation of CDK8/19 inhibitors as a new therapeutic approach to prostate cancer." (PMID 29568371, 2018). "The use of a highly specific dual CDK8/19 kinase inhibitor in prostate cancer cells induced ATR-mediated DDR resulting in caspase-independent cell death." (PMID 30693281, 2018). "In summary, our preclinical study demonstrates that CDK8/19 inhibition induces cell death in VCaP prostate cancer cells." (PMID 29568371, 2018). "Here we report that CDK8/19 modulates the gene expression of cell cycle regulators and thereby maintains the proper G1/S transition in prostate cancer cells." (PMID 29568371, 2018). "In CDK8/19 inhibitor-sensitive prostate cancer cells, we found that c-Myc depletion prevents premature G1/S transition and the subsequent DDR resulting from CDK8/19 inhibition." (PMID 29568371, 2018). "In VCaP prostate cancer cells, treatment with T-474 or T-418 suppressed the phosphorylation of the known CDK8 substrate STAT1 at Ser727 both in the absence and in the presence of IFN-γ, which stimulates CDK8-mediated STAT1 phosphorylation." (PMID 29568371, 2018). "The data presented here show that inhibition of CDK8/19 by the compounds and dual depletion of CDK8/19 by siRNAs suppressed the proliferation of VCaP prostate cancer cells." (PMID 29568371, 2018). "In CDK8/19 inhibitor-sensitive prostate cancer cells, the compounds reduced the population of G1 phase cells and elevated that of S phase cells through the modulation of G1/S transition regulators at the level of mRNA expression." (PMID 29568371, 2018).
prostate carcinoma (continued). "Our study revealed that MED12 and CDK8/19 regulate AR activity and that their inhibition may modulate response to enzalutamide in prostate cancer." (PMID 39253786, 2024). "In the current study, to characterize the mechanism by which CDK8/19 contributes to the proliferation of prostate cancer cells, we primarily utilized prostate cancer VCaP cells, which displayed the highest sensitivity to CDK8/19 inhibition among the prostate cancer cells tested." (PMID 29568371, 2018). "However, despite their importance as potential therapeutic targets for prostate cancer, the function and importance of CDK8/19 in prostate cancer remain poorly understood." (PMID 29568371, 2018). "Furthermore, we explored the biological roles of CDK8/19 in prostate cancer cells as well." (PMID 29568371, 2018). "Preclinical studies with T-474 and T-418, two structurally distinct CDK8/CDK19 inhibitors, demonstrated induction of prostate cancer cell death and significant anti-tumour activity in CRPC xenografts." (PMID 40163908, 2025). "MED12 mRNA expression was positively correlated with CDK8 and CDK19 gene expression in multiple primary prostate cancer tissue datasets, as expected by their common presence in the kinase module." (PMID 39253786, 2024). "In contrast, CDK19 knockout had a stronger effect than CDK8 knockout on STAT1 S727 phosphorylation and a similar effect on gene expression in 22Rv1 prostate carcinoma cells that overexpress CDK19 relative to CDK8." (PMID 37378433, 2023). "Studies have shown that CDK8/19 inhibits premature G1/S conversion and ATR-dependent cell death in inducible prostate cancer cells." (PMID 35451651, 2022). "We then investigated the expression of CDK8 and CDK19 in several commercially available prostate cancer cell lines." (PMID 29568371, 2018). "Thus, our data suggest that inhibition of CDK8/19 by our compounds contributes to anti-proliferative activity in prostate cancer cells both in vitro and in vivo, although it remains possible that the effects may be influenced by the inhibition of a protein other than CDK8/19." (PMID 29568371, 2018). "This gene inhibits hepatocellular carcinoma by regulating PHF19, regulates rectal cancer through CDK8, regulates osteosarcoma by inhibiting NKD1, regulates prostate cancer through Fra-1 or RPS6KB1." (PMID 28498798, 2017). "Furthermore, a previous study has also focused on high expression of both CDK8 and CDK19 in prostate cancer metastases." (PMID 33868579, 2021). "It is possible that CDK19, the paralog of CDK8, can compensate for the loss of CDK8 in the adult organism in non-transformed tissues, as proposed in NK43 and prostate cancer cells." (PMID 31628323, 2019). "In addition to confirming the previously reported survival correlations for breast and prostate cancers, several new tumor types showed a correlation between higher CDK8 levels and shorter survival, suggesting that these cancers could be potential targets for CDK8/19 inhibitor therapy." (PMID 31382571, 2019). "Although high expression of CDK8/19 has been demonstrated in prostate cancer, its function has not been thoroughly examined." (PMID 29568371, 2018). "Independent inhibition of CDK8/19’s kinase activity does not significantly impact steady-state growth in vitro in most tested cancers except for some leukemia, and moderate responses in some breast, colon, and prostate cancers." (PMID 40149277, 2025). "Recent evidence supports the idea that cyclin-dependent kinase 8 (CDK8) may represent a potential drug target for breast and prostate cancer, although no CDK8 inhibitors have entered the clinics." (PMID 31248103, 2019).
acute myeloid leukemia (20 papers, 2015 to 2026). Acute myeloid leukemia (AML) is a group of neoplasms arising from precursor cells committed to the myeloid cell-line differentiation. "Another recent study has demonstrated that Cdk8 regulates the key genes associated with SEs in acute myeloid leukaemia (AML) cells." (PMID 30814546, 2019). "CDK8 inhibitors have been shown to suppress proliferation in several types of cancer, including ER-positive breast cancer and acute myeloid leukemia." (PMID 41493967, 2026). "The most CDK8/19 inhibitor sensitive cell model in the soft agar assays was one of the two acute myeloid leukaemia (AML) cell lines, Nomo-1, included in the cell panel." (PMID 27935476, 2016). "SEL120-34A is a CDK8/19 subunit inhibitor that reduces tumor growth in acute myeloid leukemia." (PMID 39253786, 2024). "It has been reported that CDK8 plays a key role in acute myeloid leukaemia." (PMID 38258519, 2024). "Similarly, in acute myeloid leukaemia, CDK8/19 bind superenhancers and their chemical inhibition further activates enhancer activity." (PMID 36545778, 2023). "Additionally, cortistatin A, a natural product inhibitor of CDK8/19, has been shown to demonstrate antitumor activity in acute myelogenous leukemia (AML) cells." (PMID 29568371, 2018). "This indicates an increased SE number upon CDK8/19 inhibition, which agrees with prior observations in acute myeloid leukemia (AML) cells and human and mouse embryonic stem cells." (PMID 39764110, 2024). "Mediator-associated kinases cyclin-dependent kinase 8 (CDK8) and CDK19 prevent the increased activation of key super-enhancer-associated genes in acute myeloid leukemia (AML) cells." (PMID 37190100, 2023). "CDK8-ChIPseq in the acute myeloid leukemia (AML) cell line of MOLM-14 cells (mixed lineage leukemia fusion MLL-AF9) has found CDK8 on super-enhancers (SE) paralleled by the binding of MED1 and BRD4." (PMID 31248103, 2019). "SEL120-34A, the CDK8/19 inhibitor used in our study, is currently in a phase 1B clinical trial (NCT04021368) for acute myeloid leukemia." (PMID 39253786, 2024). "An example supporting redundant functions for CDK8 and CDK19 was reported in acute myeloid leukemia cells treated with the CDK8/CDK19 kinase inhibitor CA." (PMID 28416637, 2017).
leukemia (19 papers, 2014 to 2025). A malignant (clonal) hematologic disorder, involving hematopoietic stem cells and characterized by the presence of primitive or atypical myeloid or lymphoid cells in the bone marrow and the blood. "Loss of CDK8 in leukemia mouse models significantly enhances disease latency and prevents disease maintenance, specifically deregulating the mTOR signaling pathway." (PMID 39800748, 2025). "Loss of CDK8 in leukemia mouse models significantly enhances disease latency and prevents disease maintenance." (PMID 31628323, 2019). "Mice with a point mutation of serine 727 to alanine (Stat1S727A), the putative CDK8 phosphorylation site, are less susceptible to leukemia, other NK cell-surveilled tumors, and cancer metastasis." (PMID 31248103, 2019). "While CDK8/19 potentiate the induction of transcription by several signals, these kinases also inhibit Mediator-dependent transcription of super-enhancer associated genes which underlies their role in a subset of leukemias." (PMID 39955308, 2025). "Furthermore, this result can explain why CDK8/19 inhibition in leukemia cells increased the expression of genes associated with super-enhancers (which are characterized by increased Mediator binding), leading to leukemia suppression." (PMID 37378433, 2023). "Several CDK8/19i have reached clinical trials in patients with solid tumors and leukemias (clinicaltrials.gov NCT03065010, NCT04021368, NCT05052255, NCT05300438)." (PMID 39955308, 2025). "30,32 Notably, CDK8/19 inhibitors have reached clinical trials for solid tumors and leukemias (clinicaltrials.govNCT03065010, NCT04021368, NCT05052255, NCT05300438), however no prior study has assessed their utility in ovarian cancer models." (PMID 38106208, 2023). "Our preliminary investigations suggest that CDK8 interacts with the mTOR signaling pathway not only in a subset of leukemia patients but also in a range of solid cancers." (PMID 31628323, 2019). "Since CDK8/19 regulate transcription but not cell cycle progression, very few cancers, primarily a subset of leukemias, were found to require CDK8/19 for their proliferation." (PMID 31382571, 2019). "As Cdk8/Cdk19 inhibition has been reported to suppress cell proliferation in leukemia, we further analyzed the cell proliferation by CFSE labeling in the presence of CCT251921." (PMID 31552016, 2019). "The pronounced anti-proliferative effects of Cdk8 deletion in murine leukemia cells were unexpected and indicate the unique role of CDK8 downstream of BCR-ABL1p185+ in murine B-ALL." (PMID 31628323, 2019). "A number of small-molecule CDK8/19 inhibitors have been developed; such inhibitors showed in vivo therapeutic effects in leukemia, lung, breast, colon and prostate cancers." (PMID 31717492, 2019). "Overall, the lack of structural similarities, comparable affinity to CDK8 and selectivity of these probes enabled studies on CDK8-related processes in leukemia cells." (PMID 28422713, 2017). "The first evidence for single-agent activity of CDK8/19 inhibitors was reported for a subset of leukemia cell lines, where CDK8/19 inhibition had a strong anti-proliferative effect through hyper-activating super-enhancer-associated genes in such leukemias." (PMID 28147342, 2017). "Our studies confirmed differential activity of selective CDK8 inhibitors on leukemia cells in vitro." (PMID 28422713, 2017). "Our findings identify CDK8 as a key mediator of BCR-ABL1-driven leukemia." (PMID 31628323, 2019). "CDK8 and CDK19 were found to cooperate with each other in supporting leukemia cell growth, stimulating NFκB-induced transcription and Dengue virus replication." (PMID 37378433, 2023). "To evaluate the phenotypic effects of CDK8 and CDK19 in other cell lines, we have generated HAP1 leukemia derivatives with the knockout of CDK8, CDK19 or both CDK8 and CDK19 (dKO)." (PMID 37378433, 2023).
leukemia (continued). "Although murine leukemia cells (BCR-ABL1p185+) contain high levels of CDK6, CDK7, CDK8, CDK9, and CDK19, knockdown of CDK6, CDK7, CDK9, or CDK19 has little effect on cell survival and proliferation in an inducible system." (PMID 31628323, 2019). "Kinase inhibition with Senexin B or MSC causes only minor effects on transcription, whereas the deletion of CDK8 significantly affects transcriptional responses and critical signaling pathways in BCR-ABL1p185+-driven leukemia." (PMID 31628323, 2019). "Our studies and those of other groups indicated moderate or low activity of known CDK8 inhibitors on CRC cell lines in vitro, therefore we have focused on leukemia cells which were found to be sensitive to CA." (PMID 28422713, 2017). "Flavopiridol is an inhibitor of cyclin-dependent kinases (CDKs) (including CDK1, CDK2, CDK4, CDK5, CDK6, CDK7, CDK8, and CDK9) and has been investigated for the treatment of several types of cancers, including leukemia, liver cancer, and renal cancer, in clinical phase 2 trials (24, –, 26)." (PMID 31822599, 2019). "To determine whether pharmacological inhibition of CDK8 regulates viability of leukemia cells, we used SEL120-34A and two other CDK8 inhibitors, namely Senexin B, and CCT251545." (PMID 28422713, 2017). "Here, the authors show that CDK8, independent of its kinase activity, regulates mTOR signalling for the maintenance of BCR-ABL1+ leukemia, and that the dual inhibition of CDK8 and mTOR signalling induces apoptosis in these cells." (PMID 31628323, 2019).